IL10 (interleukin 10)
Diseases named in the same sentence as IL10 in open-access papers (continued):
Sharing a sentence is not in itself a finding about the gene and the disease.
osteoarthritis (continued). "Our goal was to quantify the dose-related effects of meloxicam treatment in the subchondral bone-involving, late phase of mono-iodoacetate-induced osteoarthritis, and to follow the levels of serum IL-6, IL-10 and TNFα, as markers of systemic inflammation." (PMID 28413731, 2017). "IL-10, which has a chondroprotective effect, is elevated in the cartilage and synovium of patients with osteoarthritis and acts as a stimulator of chondrocyte proliferation." (PMID 28929115, 2017). "Additionally, IL-6 is associated with osteoarthritis related cartilage loss in and MIP-1β and IL-10 concentrations are increased in the synovial fluid of osteoarthritis patients." (PMID 41185633, 2025). "TGF-β1 and IL-10 interplayed with each other in the osteoarthritis rat model." (PMID 38892016, 2024). "Serum levels of TGF-β1 were increased but those of IL-10 were decreased in osteoarthritis rats." (PMID 38892016, 2024). "Key search terms were:Osteoarthritis, Interleukin-4, and Interleukin-10." (PMID 35549461, 2022). "The RT-PCR data manifested that the expression of M1 macrophage markers (TNF-α, IL-1β, and iNOS) were significantly upregulated, while the expression of M2 macrophage markers (IL-10 and Arg-1) was significantly downregulated in synovial tissues of osteoarthritis patients." (PMID 34652255, 2021). "Carboxymethyl chitosan could attenuate inducible nitric oxide synthase and protect against osteoarthritis through the IL-10/JAK1/STAT3 pathway." (PMID 31182999, 2019). "In addition, IL-10 levels were elevated in models of rheumatoid arthritis and osteoarthritis." (PMID 36768679, 2023). "In addition, IL-10 levels were up-regulated in rheumatoid arthritis and osteoarthritis models." (PMID 36186138, 2022). "Articular chondrocytes from MT-COMP/CHOP−/− mice displayed higher IL-10 and lower TNFα levels, which influenced key molecules such as SIRT1 and MMP-13, both critical to joint health and osteoarthritis progression." (PMID 39795874, 2024). "The pathogenesis of osteoarthritis involves the activation of the inflammatory cascade through the stimulation of various cytokines such as TNF-α, IL-10, IL-8, and IL-1β." (PMID 38327525, 2024). "IL-10, an anti-inflammatory cytokine, exerts a neuroprotective and pain-relieving effect in CIPN, osteoarthritis, and chronic constriction injury-induced neuropathic pain." (PMID 36774519, 2023). "We next examined the levels of TNF-α, IL-6, IL-10 and vascular endothelial growth factor (VEGF) in the serum samples of experimental animals after induction of osteoarthritis." (PMID 35887046, 2022). "Several cytokines (such as IL-1β, lL-6, IL-8, IL-10, and TNF-α) and MMPs have been reported to be elevated in the joint space of patients with osteoarthritis." (PMID 34034772, 2021). "We additionally performed chemical hyperalgesia in osteoarthritis DBA1/J and IL-10-knock-out (IL-10−/−) mice." (PMID 30218055, 2018). "In the study of osteoarthritis, the production of OPG can be promoted by dandelion's ability to inhibit the concentration of RANKL and increase the production of TNF-α and IL-10 in serum, manifesting as an anti-inflammatory effect." (PMID 28572831, 2017). "Moreover, a strong correlation was observed between synovial fluid and synovial tissue concentrations of IL-1β, IL-10, and TNF-α in degenerative joint disease." (PMID 40649748, 2025). "The purpose of this study was to investigate the influence of moderate physical activity (MPA) on the expression of osteoarthritis (OA)-related (IL-1β, IL-6, TNF-α, MMP-13) and anti-inflammatory and chondroprotective (IL-4, IL-10, lubricin) biomarkers in the synovium of an OA-induced rat model." (PMID 30691048, 2019). "Although IL-10 therapy can alleviate neuropathic pain, IL-10 has a short half-life under physiological conditions and the plasmid-based DNA therapy which showed promising results on canines with osteoarthritis is not yet FDA approved." (PMID 36774519, 2023).
osteoarthritis (continued). "Increased circulating levels of IL-6 and IL-10 have been reported in painful osteoarthritis, but this reaction might be absent in the late-disease phase." (PMID 28413731, 2017). "Besides, a negative correlation of GAS‐5 with IL‐10 was also observed in osteoarthritis." (PMID 34936242, 2022).
Alzheimer disease (61 papers, 2007 to 2026). A progressive, neurodegenerative disease characterized by loss of function and death of nerve cells in several areas of the brain leading to loss of cognitive function such as memory and language. "Elevated levels of IL-1β, IL-6, MCP-1, and TNF-α, alongside reduced IL-8 and IL-10 levels, suggest a robust inflammatory response associated with Alzheimer’s disease." (PMID 40711681, 2025). "Several studies have demonstrated that IL-10 is associated with a variety of neurological diseases, such as multiple sclerosis (MS), Alzheimer’s disease, Parkinson’s disease and systemic lupus erythaematosus." (PMID 32532251, 2020). "Polymorphisms at the promoter region of IL10 gene are associated with several diseases, including autoimmune, infectious, cancer, Alzheimer's disease (AD), and lymphoblastic leukemia." (PMID 23213548, 2012). "IL-10, for example, is currently discussed by others as a risk factor for Alzheimer’s disease." (PMID 36085081, 2022). "Also, meta-analysis has recently revealed an association between IL-10 -1082A/G and the risk of developing the Alzheimer’s disease in a Brazilian cohort, in a way that A allele carriers (AA+AG) demonstrated a higher risk of the disease in comparison with the homozygote GG." (PMID 32050932, 2020). "In the context of Alzheimer’s disease, introducing IL-10 into the brains of transgenic mice with the amyloid precursor protein resulted in the accumulation of Aβ and a decrease in its phagocytosis by microglia." (PMID 41463495, 2025). "Accordingly, IL-10 plays a crucial role in modulating neuroinflammation and is considered an important biomarker for both the diagnosis and progression of Alzheimer’s disease." (PMID 40565209, 2025). "IL-10 was demonstrated to have inhibitory effects on microglial phagocytosis of amyloid-beta protein in a mouse model of Alzheimer’s disease, with reversal of phagocytosis inhibition later demonstrated in an IL-10 knock-out mouse model." (PMID 39369199, 2024). "Further, in the amyloid precursor protein/presenilin 1 (AAP/PS1) model of Alzheimer’s disease, IL-10 knockout mice exhibit decreased amyloid-β deposits in their hippocampus and cortex." (PMID 36992299, 2023). "Previous studies have shown that IL-10 expression in the hippocampus of transgenic mice with Alzheimer’s disease (AD) has been shown to increase neurogenesis and enhance cognition, suggesting a neuroprotective role for IL-10 in this pathological condition." (PMID 37854349, 2023). "IL-1 beta, IL-6, IL-10, and TNF-alpha single nucleotide polymorphisms in human influence the susceptibility to Alzheimer’s disease pathology." (PMID 35966781, 2022). "Recent research has mentioned IL-10 as an anti-inflammatory cytokine related to Alzheimer disease (AD)." (PMID 34073990, 2021). "New findings have demonstrated that serum level of the cytokine IL-10 is increased in patients with Alzheimer’s disease compared to vascular dementia and Down syndrome and healthy controls." (PMID 32050932, 2020). "From molecular point of view, over-expression of IL-10 exacerbates the Alzheimer’s disease in mouse model by unexpectedly giving rise to deposition of amyloid-β (Aβ) plaques in brain." (PMID 32050932, 2020). "The inflammatory score composited of blood IL-10 and other cytokines including TNF-α, IL-23, and IL-1β was negatively associated with lower FA in patients with Alzheimer’s disease." (PMID 30792621, 2019). "Accordingly, Calogero Caruso (University of Palermo, Italy) reviewed the reports indicating an association between the risk of Alzheimer Disease (AD) and polymorphisms of genes encoding inflammatory mediators, such as IL-1β, IL-6, IL-10 and TNF-α, as well as the possible involvement of Zn." (PMID 17883856, 2007). "Finally, the most recent prospective cohort study identified elevated IL-1β and reduced IL-10 levels as predictors of Alzheimer’s disease in a clinical population of women with LLD." (PMID 39922907, 2025).
Alzheimer disease (continued). "Additionally, IL-10 has been shown to act as a neuroprotector, as IL-10 secretion promotes neurogenesis in the hippocampus of mice with Alzheimer’s disease." (PMID 39457556, 2024). "However, in other diseases such as Alzheimer’s disease, IL-10 production occurs through a mechanism involving TLR4." (PMID 32532251, 2020). "In some Alzheimer’s disease (AD) patient brains, IL-10 signaling pathway was abnormally increased." (PMID 32611425, 2020). "Since both the Alzheimer’s disease and glaucoma are age-related, an increased understanding of the role of IL-10 in these three eye disorders may open the door to future treatments." (PMID 32050932, 2020). "AAV2/1 has been utilized to target neurons for anti-inflammatory effects of dominant-negative chemokine CCL2 mutant, interleukin-10 (IL-10) in mouse models of Alzheimer’s Disease (AD) and brain-derived neurotrophic factor (BDNF) in rat models of Huntington’s Disease." (PMID 29244806, 2017). "For example, IL-10 production during Alzheimer’s disease occurs through a mechanism involving TLR4." (PMID 27881137, 2016). "However, several studies showed the detrimental effects of IL-10 in Alzheimer's disease." (PMID 33083463, 2020). "In Alzheimer's disease and neuroinflammation, microglia express IL10ra and exhibit STAT3 Tyr705 phosphorylation following IL-10 stimulation, indicating IL-10 receptor-dependent STAT3 activation." (PMID 42072370, 2026). "In Alzheimer’s disease (AD) rats, it has been demonstrated that NTN-1 concentrations in serum were positively correlated with the systemic expression of IL-10." (PMID 35095412, 2021). "In controls, cortical perfusion declined with increasing IFN-γ, IL-2, IL-4, IL-6, IL-10, IL-12p70, IL-13 and tumour necrosis factor-α (TNF-α) but these relationships were lost with progression of Alzheimer’s disease, and with infection (even in Braak stage 0–II brains)." (PMID 33723589, 2021). "As a possible reason, we proposed that the increase in the expression levels of the anti-inflammatory cytokines IL-10 and TGF-β, as well as decreased NO production had favorable effects of T. gondii infection and the pathogenesis and progression of Alzheimer’s disease in mice." (PMID 29459868, 2018). "In Alzheimer’s disease, β-amyloid plaques are surrounded by reactive glial cells (microglia and astrocytes) showing elevated expression of proinflammatory factors such as IL-1β, IL-6, TNF-α, and nitric oxide, while anti-inflammatory cytokines (TGF-β1 and IL-10) are at reduced levels." (PMID 36298702, 2022).
atopic dermatitis (60 papers, 2011 to 2026). "In a clinical trial conducted at our center, vitamin D supplementation in deficient individuals with allergic dermatitis displayed a trend toward improving IL-10 levels and quality of life." (PMID 40630332, 2025). "A recent study further demonstrated that NFATc1-deficient B cells ameliorate atopic dermatitis-associated allergic responses by significantly increasing IL-10-producing regulatory B cells." (PMID 40943049, 2025). "Direct functional evidence for the role of IL-10 was provided by adoptive transfer experiments, in which IL-10-producing B cells reduced atopic dermatitis-associated ear swelling." (PMID 40943049, 2025). "It is well established that atopic dermatitis is associated with the excessive secretion of IL-4 and IL-10 by Th2 cells, leading to the unstable production of IL-12 and the reduced secretion of IFN-γ." (PMID 40299438, 2025). "Most of these applications showed effectiveness against skin-associated diseases, such as ItP of IL-10 for atopic dermatitis, STAT3 siRNA for skin cancer, and TNF-α drug etanercept for psoriasis." (PMID 38140019, 2023). "In the current study, we are interested in quantitatively investigating the possible effect of interleukin-10 (IL-10) polymorphisms on susceptibility to atopic dermatitis." (PMID 31101031, 2019). "Different results regarding the genetic effect of IL-10 polymorphisms on the risk of atopic dermatitis were reported by individual researchers." (PMID 31101031, 2019). "We retrieved different reports containing different genetic effects of − 1082 A/G, − 819 T/C, and − 592 A/C polymorphisms within the IL-10 (interleukin-10) gene on the susceptibility to clinical atopic dermatitis." (PMID 31101031, 2019). "Along with the enrolment of new publications, it is important to conduct an updated meta-analysis to reassess the role of the IL-10 polymorphisms in the risk of atopic dermatitis." (PMID 31101031, 2019). "For example, the IL-10 -1082 A/G polymorphism was reportedly linked to susceptibility to atopic dermatitis in patients from India, Italy, and the Czech Republic." (PMID 31101031, 2019). "As with IFN-γ, deficient IL-10 responses are early markers of atopic dermatitis and are reported in infants with this disease." (PMID 21386995, 2011). "In addition, the TT genotype frequency of the IL-10 -819 T/C polymorphism in atopic dermatitis patients was higher than that in healthy control subjects in India." (PMID 31101031, 2019). "However, the CC genotype of the IL-10 -819 T/C polymorphism was also reported to be associated with an enhanced risk of severe atopic dermatitis in patients from the Czech Republic." (PMID 31101031, 2019). "However, we focused on the role of three SNPs of the IL-10 gene, one member in the interleukin gene family, in the susceptibility to atopic dermatitis in this study, based on the limitations of study publications." (PMID 31101031, 2019). "In addition, severe atopic dermatitis is associated with reduced frequency of IL-10-producing allergen-specific CD4+ T cells." (PMID 22968402, 2012). "Vitamin D plays a fundamental role in reducing inflammation, upregulating Treg cells and IL-10 production, therefore its supplementation, especially in deficient states, has been postulated as a possible treatment with promising results for autistic children and children with atopic dermatitis." (PMID 37588589, 2023). "However, human milk itself may provide the necessary immunological factors to lower severe symptoms of CMA-related atopic eczema/dermatitis syndrome, as breastfeeding has been associated with a significant increase in IL-10, a regulator of immunological response." (PMID 40290002, 2025). "Interleukins IL-4, Il-5, IL-10, IL-13 and IL-33 play an important role in atopic dermatitis patients." (PMID 40771803, 2025). "Ozonated oil effectively suppresses inflammation in an atopic dermatitis murine model by reducing Th2-dominant cytokine responses and increasing IL-10 expression." (PMID 40443591, 2025).
atopic dermatitis (continued). "Our study confirmed higher plasmatic IL-10 levels in both dupilumab-treated and untreated atopic dermatitis patients compared to the control group." (PMID 40771803, 2025). "A significant positive correlation between vitamin D and IL-10 levels was observed among individuals with allergic dermatitis." (PMID 40630332, 2025). "One of the findings was that ingestion of Lactobacillus plantarum CCFM8610 significantly improved atopic dermatitis and increased serum IL-10 levels." (PMID 40431255, 2025). "Accordingly, IL-10 from Breg cells alleviates atopic dermatitis by suppressing eosinophil activation and tissue infiltration." (PMID 41283510, 2025). "In chronic inflammatory diseases such as atopic dermatitis, L. rhamnosus activates immune cells, regulates IgE levels, and modulates Th-2 immune responses through IL-10, thereby reducing inflammatory reactions." (PMID 40615864, 2025). "Inadequate circulating vitamin D and IL-10 levels can significantly influence the course of this allergic dermatitis." (PMID 40630332, 2025). "ItP of naked IL-10 siRNA or liposome-encapsulated STAT3 siRNA showed a significant RNAi effect on rat skin of an atopic dermatitis model or the skin of melanoma-bearing mice, respectively." (PMID 38140019, 2023). "High immunoexpression of INF-γ was noted by immunohistochemistry (IHC) in inflamed regions of tissues of 12 vulvar LS while increased levels of INF-γ, IL-4, TNF-α and IL-10 were observed in atopic dermatitis." (PMID 35103930, 2022). "The first scientific reports on the regulatory role of B cells in AD arose in 2015 when a decreased number of IL-10-producing B cells was demonstrated in an Atopic Dermatitis-Like Mouse Model." (PMID 36555351, 2022). "The histamine-induced CCL18 upregulation in IL-10-activated M2 macrophages was almost similar in cells obtained from atopic dermatitis patients compared to cells from healthy control persons." (PMID 34769080, 2021). "IL-10 is overexpressed in the skin of AD patients and has an essential function for skin infiltration with eosinophils in a mouse model of atopic dermatitis." (PMID 34769080, 2021). "Atopic dermatitis increased the expression levels of IL-4, IL-13, IL-6, IL-17, IFNγ, and TNFα but decreased the expression of IL-10 in BALB/c mouse, in an SOCS1-dependent manner." (PMID 30459600, 2018). "The serum IL-10 levels in atopic eczema/dermatitis syndrome children were markedly lower than that in healthy controls." (PMID 28086216, 2017). "Increased IL-4 is also reported to suppress IL-10, exacerbating syptoms of Th2 mediated atopic dermatitis." (PMID 25730203, 2015). "The role of interleukins IL-4, IL-5, IL-10, IL-13 and IL-33 in atopic dermatitis." (PMID 40771803, 2025). "In chronic inflammatory diseases such as atopic dermatitis, L. rhamnosus activates immune cells to regulate immunoglobulin E (IgE) levels and modulates T-helper cell type 2 (Th-2) immune responses through interleukin-10 (IL-10), leading to a reduction in inflammation." (PMID 40615864, 2025). "Lower vitamin D and IL-10 levels may have a greater impact on the quality of life among individuals with allergic dermatitis." (PMID 40630332, 2025). "Atopic dermatitis patients displayed a higher percentage of IL-10-producing Breg cells, indicating that these cells promote the differentiation of B cells into Bregs, which produce more anti-inflammatory IL-10, thus alleviating atopic dermatitis symptoms." (PMID 41283510, 2025). "Lactococcus lactis LB 1022 increased IL-10 levels both in vitro and in mice with atopic dermatitis." (PMID 39594091, 2024). "Moreover, gallic acid increased the expression levels of IL-10 in mice models with atopic dermatitis-like skin inflammation." (PMID 39227945, 2024). "Furthermore, in patients with atopic dermatitis, the ability of regulatory B cells to produce IL-10 in response to IL-6 stimulation is diminished." (PMID 39767628, 2024).